AZIN2 (antizyme inhibitor 2)
Description:
Antizyme inhibitor (AZI) protein that positively regulates ornithine decarboxylase (ODC) activity and polyamine uptake. AZI is an enzymatically inactive ODC homolog that counteracts the negative effect of ODC antizymes (AZs) OAZ1, OAZ2 and OAZ3 on ODC activity by competing with ODC for antizyme-binding. Inhibits antizyme-dependent ODC degradation and releases ODC monomers from their inactive complex with antizymes, leading to formation of the catalytically active ODC homodimer and restoring polyamine production. Participates in the morphological integrity of the trans-Golgi network (TGN) and functions as a regulator of intracellular secretory vesicle trafficking.
Synonyms: ADC; ODC-p; KIAA1945; ODCP; ODC1L; AZIB1
Tractability: Small molecule: it belongs to a druggable protein family. PROTAC: UniProt records ubiquitination sites on it.
Gene: Protein-coding gene on chromosome 1 (33,081,104 to 33,123,492, forward strand). Ensembl gene ENSG00000142920.
Subcellular location: Nucleus; Cytoplasm; Cytoplasm, perinuclear region; Membrane; Cytoplasmic vesicle; Endoplasmic reticulum-Golgi intermediate compartment; Golgi apparatus, cis-Golgi network; Golgi apparatus, trans-Golgi network; Cytoplasmic granule; Cell projection, axon; Cell projection, dendrite; Perikaryon
Subcellular location (Human Protein Atlas): Cytosol
Pathways (Reactome):
Metabolism: Agmatine biosynthesis
Gene Ontology:
Molecular function: ornithine decarboxylase activator activity; protein binding; arginine decarboxylase activity; ornithine decarboxylase activity; carboxy-lyase activity; catalytic activity
Biological process: negative regulation of protein catabolic process; trans-Golgi network membrane organization; agmatine biosynthetic process; positive regulation of catalytic activity; positive regulation of polyamine transmembrane transport; spermatogenesis; polyamine biosynthetic process
Cellular component: axon; cytoplasmic vesicle; cytosol; dendrite; granular vesicle; nucleus; perikaryon; perinuclear region of cytoplasm; trans-Golgi network; transport vesicle; cis-Golgi network; cytoplasm; endoplasmic reticulum-Golgi intermediate compartment membrane; endoplasmic reticulum-Golgi intermediate compartment; Golgi apparatus; membrane; mitochondrion
Genetic constraint (gnomAD): Loss-of-function variants: 28 observed, 48.17 expected, observed/expected ratio (o/e) 0.58, 90% interval 0.43 to 0.8. The upper end of that interval is the gene's LOEUF score, 0.8, which puts it in group 3 of 6, group 1 being the genes least tolerant of losing a copy. Missense variants: 535 observed, 605.16 expected, observed/expected ratio (o/e) 0.88, 90% interval 0.82 to 0.95. Synonymous variants: 221 observed, 249.66 expected, observed/expected ratio (o/e) 0.89, 90% interval 0.79 to 0.99.
Homologues: Orthologues: chimpanzee AZIN2 (99% identical), pig AZIN2 (89% identical), macaque AZIN2 (88% identical), guinea pig AZIN2 (87% identical), mouse Azin2 (86% identical), dog AZIN2 (71% identical), rat Azin2 (70% identical), rabbit AZIN2 (70% identical), tropical clawed frog azin2 (61% identical), Drosophila melanogaster Odc1 (32% identical), Drosophila melanogaster Odc2 (30% identical), Caenorhabditis elegans F53F10.2 (25% identical). Paralogues in human: ODC1 (51% identical), AZIN1 (42% identical).
Diseases named in the same sentence as AZIN2 in open-access papers:
AZIN2 is named in the same sentence as 26 diseases in open-access papers, as found by Europe PMC text mining. Sharing a sentence is not in itself a finding about the gene and the disease. The quoted sentences say what the papers report.
colorectal cancer (2 papers, 2019 to 2023). A primary or metastatic malignant neoplasm that affects the colon or rectum. "Cox uni-and multivariable analysis of relative risk of death from colorectal cancer within 5 years by AZIN2 expression." (PMID 30768610, 2019). "We applied immunohistochemistry with antibodies to human AZIN2 on tissue micro- arrays of colorectal cancers (CRC) from 840 patients with a median follow-up of 5.1 years (range 0–25.8)." (PMID 30768610, 2019).
adenoid cystic carcinoma (1 paper, 2024). A malignant tumor arising from the epithelial cells. "High AZIN2 expression was related to well-differentiated histological type with a functioning vesicle transportation system in adenoid cystic carcinoma (ACC) tissue, which suggested that AZIN2 could be a prognostic factor for better survival of ACC patients." (PMID 38169396, 2024).
Alzheimer disease (1 paper, 2022). A progressive, neurodegenerative disease characterized by loss of function and death of nerve cells in several areas of the brain leading to loss of cognitive function such as memory and language. "Immunohistochemical studies of normal human brain samples detected the presence of AZIN2 mostly in both the white and gray matter and increased accumulation of AZIN2 in brains affected by Alzheimer’s disease." (PMID 36671399, 2022). "Moreover, research over the last decades has shown the importance of polyamines and AZIN2 in neurodegenerative conditions such as Parkinson disease or Alzheimer’s disease." (PMID 36671399, 2022).
Cognitive impairment (1 paper, 2022). Abnormal cognition is characterized by deficits in thinking, reasoning, or remembering. "Interestingly, overexpression of antizyme inhibitor 2 (hence increased ODC activity) augmented tau neuropathology and cognitive impairments in PS19 mice." (PMID 35682712, 2022).
colon carcinoma (1 paper, 2019). "Immunohistochemical staining of sections of colon cancers with antibodies to human AZIN2 revealed its elevated expression in the invasive cells of the tumor fronts." (PMID 30768610, 2019). "Based on our finding that AZIN2 is a regulator of vesicle transport and mast cell degranulation, we used a human colon cancer cell line to study the impact of AZIN2 expression on in vitro release of exosome-like material." (PMID 30768610, 2019). "Over-expression of human AZIN2 cDNA in T84 colon cancer induced accumulation of CD63-positive exosomes in the culture medium." (PMID 30768610, 2019). "Immunohistochemical stainings of sections from colon cancers revealed particularly strong AZIN2 expression in invasive cells of the tumor front, showing morphological features of EMT." (PMID 30768610, 2019).
glomerulosclerosis (1 paper, 2016). A hardening of the kidney glomerulus caused by scarring of the blood vessels. "Impairment of vesicle trafficking by targeted deletion of the vacuolar sorting protein 34 in mouse podocytes has been shown to cause glomerulosclerosis indicating the importance of an intact vesicle transport, where AZIN2 may be functionally involved." (PMID 26963840, 2016).
infertile (1 paper, 2013). "Interestingly, mutant mice with disrupted AZ3, the antizyme specific of haploid cells and putative partner of AZIN2, are infertile." (PMID 23874910, 2013).
male infertility (1 paper, 2018). The inability of the male to effect fertilization of an ovum after a specified period of unprotected intercourse. "In order to obtain further information on the types of testicular cells expressing Azin2, we analyzed the expression of Azin2, Oaz3 and Odc in the testis of two transgenic mouse models presenting male infertility: Atm-null mice and Atr-hypomorphic mice." (PMID 30566531, 2018).
mastocytoma (1 paper, 2016). A localized tumor composed of sheets of mast cells without atypia. "In addition to our previously reported expression of AZIN2 in normal mast cells and in mastocytomas we found AZIN2 in a slightly granular distribution in cytoplasm of megakaryocytes of normal bone marrow." (PMID 26963840, 2016). "We also reported expression of AZIN2 in human normal mast cell and mastocytomas." (PMID 26963840, 2016).
non-small cell lung carcinoma (1 paper, 2024). A group of at least three distinct histological types of lung cancer, including non-small cell squamous cell carcinoma, adenocarcinoma, and large cell carcinoma. "Hypoxia-induced AZIN2 high expression may contribute to cisplatin resistance by promoting the epithelial-mesenchymal transition (EMT) in non-small cell lung cancer (NSCLC)." (PMID 38169396, 2024).
tumor (7 papers, 2018 to 2026). "High tumor expression of AZIN2 predicted an unfavorable prognosis (p<0.0001, log-rank test), compared to low AZIN2 expression." (PMID 30768610, 2019). "The strongest AZIN2 expression was seen in invasive tumor cells having morphological features of epithelial-mesenchymal transition (EMT)." (PMID 30768610, 2019). "Immunohistochemistry revealed a slightly granular distribution of the cytoplasmic AZIN2 in the tumor cells." (PMID 30768610, 2019). "Here we show that increased tumor expression of AZIN2 is an independent predictor of unfavorable prognosis in CRC." (PMID 30768610, 2019). "AZIN2’s role in upregulating ODC activity might indirectly diminish the tumor-suppressive effects of OAZ2 by enhancing polyamine biosynthesis." (PMID 40032914, 2025). "Therefore the role of the concentrations of tumor-derived exosomes in the body fluids of CRC patients with cancers showing high AZIN2 expression needs to be investigated further." (PMID 30768610, 2019). "When we stratified CRC according to stage, high AZIN2 expression was a sign of unfavorable prognosis in Dukes C (Stage III) CRC (p = 0.014); 5-years DSS for patients with high AZIN2 tumor expression was 52.4% (95 CI 41.4–63.3) compared to 67.5% (95% CI 57.5–77.5) for those with low expression." (PMID 30768610, 2019). "The strongest AZIN2 expression was seen in the invasive cells of the tumor front." (PMID 30768610, 2019). "Since there are discrepant findings on the cellular location of AZIN2 in haploid cells between mouse and human testes, we decided to use the existing data on the gene expression profile between control and tumor testicular human cells to get complementary information on this subject." (PMID 30566531, 2018). "High AZIN2 expression in CRC was a sign of unfavorable prognosis (p<0.0001, log-rank test); 5-years DSS for patients with high AZIN2 tumor expression was 52.5% (95 CI 42.0–58.0) compared to 66.9% (95% CI 52.9–72.1) for those with low expression." (PMID 30768610, 2019). "Among these 20 common genes, the expression levels of CDK20, AKAP7, AZIN2, LIX1L, OSCP1, and SLFN12 were upregulated, while HLF was downregulated in TC-PD-L1+ tumours (Pattern 3 and Pattern 4)." (PMID 29921949, 2018). "Additionally, the increased expression of AZIN2, the antagonist of OAZ2, in COAD tissues suggests a competitive interplay that could influence polyamine biosynthesis and tumor dynamics." (PMID 40032914, 2025). "The histological grade of the tumor did not correlate with AZIN2 expression." (PMID 30768610, 2019).
cancer (6 papers, 2018 to 2025). A tumor composed of atypical neoplastic, often pleomorphic cells that invade other tissues. "Our findings of enhanced exosome release in vitro from cancer cells with high AZIN2 expression provide an explanation to the correlation between AZIN2 levels and prognosis in CRC." (PMID 30768610, 2019). "Given our findings of high AZIN2 expression in cancer cells with features of EMT, it is conceivable that AZIN2 constitutes a signature for EMT-associated secretory phenotype–a feature that has been found to predict poorer cancer survival." (PMID 30768610, 2019). "Enhanced AZIN2 expression was also found in cancers with mucinous histology." (PMID 30768610, 2019). "The molecular pathways regulating the enhanced AZIN2 expression in relation to EMT are under investigation like also the question of whether forced overexpression of AZIN2 directly induces EMT in cancer cells." (PMID 30768610, 2019). "AZIN2 expression was higher in cancers arising from the right colon compared to left colon, which may be due to the higher frequency of tumors with mucinous histology in the proximal colon." (PMID 30768610, 2019). "Antizyme inhibitor 2 (AZIN2) takes part in the ornithine metabolic process and is identified to be an element for a poor prognosis in CRC, actuating aggressiveness of cancer cells with morphological characters of EMT." (PMID 36035152, 2022). "There are no previous reports on the impact of AZIN2 expression in human cancer." (PMID 30768610, 2019).
AZIN2 also shares sentences with these, for which no sentence is quoted: infection (2 papers); bipolar depression (1); brain trauma (1); cutaneous mastocytosis (1); glioma (1); HIV-1 infection (1); ischemia (1); melanoma (1); mood disorder (1); Parkinson disease (1); schizophrenia (1); spinal cord injury (1); testicular germ cell tumor (1); testicular tumors (1).